PCDH15 (protocadherin related 15)
Description:
Calcium-dependent cell-adhesion protein. Essential for maintenance of normal retinal and cochlear function.
Synonyms: USH1F; CDHR15; DFNB23
Tractability: Small molecule: a high-quality ligand is known. Antibody: UniProt places it where antibodies can reach, with medium confidence; UniProt predicts a signal peptide or a membrane-spanning region; its Gene Ontology location is reachable by antibodies, with medium confidence; the Human Protein Atlas places it where antibodies can reach.
Target class: Adhesion
Gene: Protein-coding gene on chromosome 10 (53,802,771 to 55,627,942, reverse strand). Ensembl gene ENSG00000150275.
Subcellular location: Cell membrane; Secreted (Isoform 3)
Subcellular location (Human Protein Atlas): Plasma membrane; Vesicles; Focal adhesion sites; Golgi apparatus; Nucleoplasm
Pathways (Reactome):
Sensory Perception: Sensory processing of sound by inner hair cells of the cochlea; Sensory processing of sound by outer hair cells of the cochlea
Gene Ontology:
Molecular function: cell adhesion molecule binding; calcium ion binding
Biological process: equilibrioception; photoreceptor cell maintenance; sensory perception of light stimulus; sensory perception of sound; cell adhesion; visual perception; homophilic cell-cell adhesion; inner ear development
Cellular component: photoreceptor outer segment; synapse; plasma membrane; stereocilium; extracellular region; membrane
Genetic constraint (gnomAD): Loss-of-function variants: 103 observed, 148.16 expected, observed/expected ratio (o/e) 0.7, 90% interval 0.59 to 0.82. The upper end of that interval is the gene's LOEUF score, 0.82, which puts it in group 3 of 6, group 1 being the genes least tolerant of losing a copy. Missense variants: 2,081 observed, 2,063 expected, observed/expected ratio (o/e) 1.01, 90% interval 0.97 to 1.05. Synonymous variants: 765 observed, 728.76 expected, observed/expected ratio (o/e) 1.05, 90% interval 0.99 to 1.11.
Gene-disease validity (ClinGen):
ClinGen rates the evidence that PCDH15 causes each of these diseases.
Usher syndrome type 1 (autosomal recessive): Definitive. A syndrome characterized by congenital, bilateral, severe sensorineural hearing loss, abnormalities in the vestibular system, and adolescent-onset retinitis pigmentosa.
nonsyndromic genetic hearing loss (autosomal recessive): Limited.
Homologues: Orthologues: chimpanzee PCDH15 (85% identical), macaque PCDH15 (85% identical), rabbit PCDH15 (83% identical), dog PCDH15 (83% identical), rat Pcdh15 (81% identical), mouse Pcdh15 (81% identical), guinea pig PCDH15 (80% identical), tropical clawed frog pcdh15 (60% identical), zebrafish pcdh15b (56% identical), zebrafish pcdh15a (56% identical). Paralogues in human: PCDH10 (15% identical), PCDHGB5 (14% identical), PCDHGA5 (14% identical), PCDHGB1 (14% identical), PCDHGB4 (14% identical), PCDHGA10 (14% identical), PCDHGA11 (14% identical), PCDHGA12 (14% identical), PCDHGA6 (14% identical), PCDHGA8 (14% identical), PCDHGB2 (14% identical), PCDHAC2 (14% identical), and 49 more.
Diseases named in the same sentence as PCDH15 in open-access papers:
PCDH15 is named in the same sentence as 89 diseases in open-access papers, as found by Europe PMC text mining. Sharing a sentence is not in itself a finding about the gene and the disease. The quoted sentences say what the papers report.
Usher syndrome (76 papers, 2007 to 2025). A syndromic diseae characterized by the association of sensorineural deafness (usually congenital) with retinitis pigmentosa and progressive vision loss. "Mutant alleles of PCDH15 are responsible for both Usher syndrome type 1F (USH1F) and autosomal recessive deafness (DFNB23)." (PMID 40486680, 2025). "Variants in PCDH15 contributed to Usher syndrome type 1F in patients 1 and 5, whereas the remaining four had isolated deafness (DFNB23)." (PMID 40486680, 2025). "Conversely, PCDH15 mutations were a prevalent cause of type 1 Usher syndrome, responsible for over 15% of such cases in both Spanish and North American cohorts, but were identified in just a single family in this study." (PMID 38189974, 2024). "Pathogenic variants in PCDH15 cause Usher syndrome, a condition characterized by hearing and vision loss." (PMID 38742929, 2024). "This mutation (Δex6) simulated a rare variant found in Usher syndrome patients [50-bp del NM_001384140.1(PCDH15): c.475–2204_594 + 1766 del]." (PMID 37595869, 2023). "In one such case, variants in the PCDH15 gene have been associated with Usher syndrome (MIM 601067), which presents with hearing and vision loss, and matched the clinical phenotype for this patient." (PMID 36999085, 2023). "CDH23 is located on chromosome 10q21.1 and is in the MYP15 region of the HM locus, like PCDH15, which is also associated with Usher syndrome and retinitis pigmentosa." (PMID 37884635, 2023). "Five genes (USH2A, USH1G, USH1C, MYO7A, and PCDH15) were associated with Usher syndrome from Africa." (PMID 34609590, 2022). "Here we present a case of Usher syndrome type 1F (USH1F) with a novel homozygous variant in the calcium-dependent cell-cell adhesion protocadherin-15 (PCDH15) gene." (PMID 36384460, 2022). "Among the protocadherin superfamily members, PCDH15 pathogenic variants cause Usher syndrome following an autosomal recessive inheritance pattern." (PMID 34948243, 2021). "PCDH15 (OMIM *605514) encodes for protocadherin 15 and is mutated in Usher syndrome types 1D/F and 1F, as well as in non-syndromic autosomal recessive deafness DFNB23." (PMID 34562878, 2021). "PCDH15 gene is associated with autosomal recessive HL type 23 and autosomal recessive/digenic Usher syndrome." (PMID 34440452, 2021). "Mutations in the PCDH15 gene result in one of the most severe forms of Usher syndrome, type 1F (USH1F) which was first described in 1997." (PMID 33193648, 2020). "Mutations of PCDH15, encoding protocadherin 15, are responsible for inducing combined hearing and vision impairment (type 1 Usher syndrome; USH1F) or nonsyndromic deafness (DFNB23)." (PMID 29692870, 2018). "Mutations in PCDH15 are associated with Usher syndrome type 1F, a recessive disease characterised by retinopathy and hearing loss." (PMID 24705015, 2014). "Several of the top candidate genes include EEF1A1, ROBO1, PLXNA4, SLIT3, NRP1, and NOTCH2, as well as genes associated with the Usher syndrome, PCDH15 and USH2A, and are plausible candidates contributing to the developmental defects in Gbx2−/− mice." (PMID 23144817, 2012). "This region was further refined in a study of two Pakistani families segregating Usher syndrome type 1F that demonstrated two homozygous mutations (splice site acceptor mutation and nonsense mutation) in the 33 exon PCDH15 gene." (PMID 17327828, 2007). "Notably, the KLHL29 gene, which is associated with Bardet–Biedl syndrome in humans, and Pcdh15, which is associated with Usher syndrome, were amongthe top 10 DEGs." (PMID 40589789, 2025). "CDH23 interacts with PCDH15 in the tip links of inner hair cells, and digenic interactions have been observed in both mice and humans, suggesting possible modification among genes associated with Usher syndrome." (PMID 40486680, 2025). "In addition to Hutterites, the PCDH15 c.1103delT (p.Leu368Trpfs*58) variant was detected only in Slovenian patients with Usher syndrome suggesting a Slavic origin of this allele in Hutterites." (PMID 39273284, 2024).
Usher syndrome (continued). "The PCDH15 c.1103delT (p.Leu368Trpfs*58) variant is associated with Usher syndrome." (PMID 39273284, 2024). "Mutations in the PCDH15 gene cause Usher syndrome type 1F in humans." (PMID 36611792, 2023). "In humans, mutations in PCDH15 can cause isolated deafness or Usher syndrome type 1 F (USH1F)." (PMID 37100771, 2023). "Our proteomic data showed significant changes in the levels of proteins for retinitis pigmentosa (RPE65, RP2, MERTK, and RBP3), X-linked retinoschisis (RS1), CRB1-retinal dystrophy (CRB1), Usher syndrome (PCDH15), and Leber congenital amaurosis (RD3 and KCNJ13)." (PMID 36139394, 2022). "PCDH15 is best known for its role in hereditary hearing loss (Usher syndrome type 1F)." (PMID 36233050, 2022). "In conclusion, this work describing the first ever large inversion in chromosome 10 leading to Usher syndrome extends the mutational spectrum of the PCDH15 gene and emphasizes the importance of considering the identification of balanced SVs for exhaustive molecular diagnostics." (PMID 32714370, 2020). "Mutations in PCDH15 and MYO7A may lead to both non-syndromic hearing loss (DFNB23 and DFNB2, respectively) and Usher syndrome type 1 (USH1F and USH1B, respectively)." (PMID 26011067, 2015). "Mutations in CDH23 were found to cause Usher syndrome type 1D (USH1D) and nonsyndromic deafness DFNB12, while mutations in PCDH15 were associated with Usher syndrome type 1F (USH1F) and nonsyndromic deafness DFNB23." (PMID 40943399, 2025). "In GER (CD−M3), Tecta, Pcdh15, and Cdc14a were associated with NSHL, Slitrk6 with deafness and myopia, Pcdh15 with Usher syndrome, Eya1 with branchiootorenal syndrome, Chd7 with CHARGE syndrome, and Cdc14a with hearing impairment and infertile male syndrome." (PMID 39684410, 2024). "Cad99C is homologous to the Usher syndrome gene PCDH15 while Msp300 and koi correspond to the nuclear membrane anchoring genes SYNE4 and SUN1, respectively." (PMID 38412189, 2024). "Mutations of PCDH15 also cause similar disorders, including autosomal recessive deafness 23 (OMIM: 609533) and Usher syndrome type 1D (OMIM: 601067) or Usher syndrome type 1F (OMIM: 602083)." (PMID 36468022, 2022). "PCDH15, CDH23 and MYO7A: While these three genes are known for Usher syndrome, they have AR nonsyndromic forms of hearing loss." (PMID 33924653, 2021). "Three patients had hearing loss and were diagnosed with Usher syndrome, and they independently carried CDH23, PCDH15, and USH1G variants." (PMID 34721897, 2021). "Some PSGs that form hair bundle links are also implicated in vision; for example, PCDH15, USH2A, and ADGRV1 are all involved in Usher syndrome, congenital deafness due to stereocilia disorganization with associated progressive retinitis pigmentosa." (PMID 34137817, 2021). "Currently, up to 13 genes have been associated with Usher syndrome: MYO7A, USH1C, CDH23, PCDH15, USH1G, and CIB2 are responsible for USH1, although the role of CIB2 in the Usher syndrome has recently been put on doubt." (PMID 31231422, 2019). "The “rarest” Usher syndrome genes with mutations were as follows: USH1G (1 patient), CLRN1 (1 patient), PCDH15 (2 patients), and USH1C (4x)." (PMID 28944237, 2017). "We show that ubr3 mutations are phenotypically similar to known pathogenic variants of Myosin II and that Ubr3 physically and genetically interacts with Drosophila homologues of the Usher syndrome proteins Protocadherin 15 (Pcdh15) and Sans." (PMID 27331610, 2016). "We report here four patients, who had probable pathogenic mutations in two different Usher syndrome type 1 genes, and one case of MYO7A/PCDH15 digenic inheritance." (PMID 24618850, 2014). "Families 5, 6, and 7 appeared to have candidate mutations or variants in MYO7A, CDH23, PCDH15, and USH2A, all of which are associated with Usher syndrome." (PMID 24164807, 2013). "Mutations in Usher syndrome-related genes were detected in three families, including one double heterozygous mutation of CDH23 and PCDH15." (PMID 24164807, 2013).
Usher syndrome (continued). "Alterations in a number of proteins, including the cell-cell adhesion protein PCDH15 and transmembrane protein USH2A, are thought to directly contribute to the defects associated with Usher syndrome." (PMID 23144817, 2012). "Mutations in CDH23, PCDH15, VLGR1 and clarin-1 cause Usher syndrome, characterized by congenital deafness, vestibular dysfunction and retinitis pigmentosa." (PMID 22363448, 2012). "Mutant alleles in PCDH15 may contribute to isolated forms of profound deafness (DFNB23, phenotype ID: 609533) and Usher syndrome subtype USH1F, characterized by congenital profound sensorineural hearing loss, progressive RP, and vestibular impairment." (PMID 40486680, 2025). "Usher syndrome type 1 (USH1) is a genetic disorder that is characterized by severe hearing loss and retinitis pigmentosa; furthermore, variants in the Pcdh15 gene have been identified in families with Usher syndrome type 1F (USH1F)." (PMID 38806495, 2024). "Potential causative variants were identified in genes associated with nonsyndromic hearing loss (CIB2, COL11A1, ILDR1, MYO15A, TMPRSS3, and WFS1), nonsyndromic hearing loss or Usher syndrome (CDH23, MYO7A, PCDH15, and USH2A), and other syndromic forms of hearing loss (CHD7, OPA1, and SPTLC1)." (PMID 34837038, 2022). "In this study, one patient from family OFT-00177 with EoHM and retinal dystrophy had two VUS, one in CEP290 (a gene related to Bardet-Biedl syndrome, Meckel syndrome, Joubert syndrome and Senior-Løken syndrome) and the other in PCDH15 (a gene responsible for Usher syndrome)." (PMID 35457050, 2022). "PCDH15 and CDH23 are the pathogenic genes for Usher syndrome." (PMID 36568381, 2022). "Some Usher syndrome patients were found to carry mutations in MYO7A, and PCDH15 genes." (PMID 34609590, 2022). "The medical examination of MYO7A and PCDH15 patients showed that they had Usher syndrome type 1." (PMID 34609590, 2022). "Rare biallelic variants in PCDH12 (OMIM 605622) and PCDH15 (OMIM 605514) have been reported in patients with diencephalic–mesencephalic junction dysplasia syndrome 1 (DMJDS1; OMIM 251280), Usher syndrome type 1F (USH1F, OMIM 602083), and nonsyndromic hearing loss (DFNB23; OMIM 609533), respectively." (PMID 34244665, 2021). "The PCDH15 is located on chromosome 10q21.1, which coincides with the MYP15 region of the HM locus, and has been identified to be associated with the development of Usher syndrome, which is associated with intellectual disability, EEG abnormalities or schizophrenia, in addition to ocular symptoms." (PMID 37884635, 2023). "Five patients had obtained a molecular genetic diagnosis of Usher syndrome (CDH23, n = 2; PCDH15, n = 1; USH2A, n = 2) from a genetic screen for early sensorineuronal hearing loss." (PMID 39596324, 2024). "The fly orthologue candidates of Usher syndrome genes MYO7A (crinkled in fly), WHRN (dyschonic in fly), USH1C (CG5921 in fly), and PCDH15 (Cad99C in fly) were localized or expressed in the actin-rich scolopale cells, consistent with our previous findings." (PMID 38412189, 2024). "Genetic counseling prior to analysis of genes potentially revealing Usher syndrome (CDH23, PCDH15 and MYO7A) is important and this should be explained to parents who agree to have this type of diagnostics performed for their child." (PMID 22607986, 2012). "Usher syndrome type 1F (USH1F), resulting from mutations in the protocadherin-15 (PCDH15) gene, is characterized by congenital lack of hearing and balance, and progressive blindness in the form of retinitis pigmentosa." (PMID 39441757, 2024). "Usher syndrome type 1 F (USH1F), caused by mutations in the protocadherin-15 gene (PCDH15), is characterized by congenital deafness, lack of balance, and progressive blindness." (PMID 37100771, 2023). "It was reported that missense variants of the PCDH15 gene led to NSHL, while other variants (frameshift, nonsense, splicing, and large fragment deletion) caused Usher syndrome (type 1F) (MIM602083)." (PMID 36568381, 2022).
Usher syndrome (continued). "One patient was found to be compound heterozygous for mutations in two different genes, one in PCDH15 and the other in CDH23; since proteins interact with one another and form dynamic protein complexes, digenic or oligogenic inheritance of Usher syndrome is not surprising." (PMID 21738395, 2011).
deafness (41 papers, 2008 to 2025). An inherited or acquired condition characterized by the complete loss of the ability to hear from one or both ears. "Pcdh15av-2J mice carry a spontaneous mutation at the Pcdh15 locus and are characterized by head tossing, circling, and deafness." (PMID 38806495, 2024). "We show that the mutation, R113G, in Pcdh15 that is associated with congenital deafness removes the catch region dynamics of the individual tip-link." (PMID 38383683, 2024). "Mutations in PCDH15 cause deafness and blindness in Usher syndrome 1 F, but gene therapy is difficult because the PCDH15 sequence is too large for AAV vectors." (PMID 37100771, 2023). "In the Ames waltzer mice, recessive mutations of Pcdh15 cause deafness due to disorganized stereocilia bundles and degeneration of inner ear neuroepithelia." (PMID 30029624, 2018). "Protocadherin 15 (PCDH15) mutations in which causes inherited deafness called usher1F syndrome is the likely target gene of two HS HCSNs found in this study." (PMID 27289096, 2016). "CDH23 or PCDH15 were included in our study set of genes due to their known causal roles in inherited forms of deafness." (PMID 26264041, 2015). "This will also serve as a basis for the development of gene therapy for deafness caused by PCDH15 defects." (PMID 24940003, 2014). "Recessive mutations in genes coding for cadherin 23 (Cdh23) and protocadherin 15 (Pcdh15) cause deafness in both mice and humans." (PMID 21119891, 2010). "Lastly, the retinal-specific consequences found in our pcdh15b mutants, and not in pcdh15a mutants, may provide insight into why particular mutations in PCDH15 are only associated with non-syndromic deafness, whereas others lead to USH1." (PMID 34668518, 2021). "Our studies illuminate the architecture of the PCDH15-LHFPL5 complex, localize mutations associated with deafness, and shed new light on how forces in the PCDH15 tether may be transduced into the stereocilia membrane." (PMID 30070639, 2018). "Given that some deafness-causing mutations are known to be localized to alternative exons (i.e. R643X in PCDH15 and R500X in TRIC), understanding the regulation of alternative exon choice in the inner ear is expected to create therapeutic opportunities for the prevention of deafness." (PMID 23055939, 2012). "In summary, the study of deafness mechanisms caused by mutations in CDH23 and PCDH15 has progressed from the identification of functional mutations to in-depth investigations of structure-function relationships." (PMID 41049429, 2025). "These hair bundle defects are similar to those described in other Pcdh15 mutants, which also exhibit deafness and reflect the role of PCDH15 as a component of the tip links between adjacent stereocilia." (PMID 35296311, 2022). "The other 6 variants were associated with recessive forms of deafness (TMPRSS3, GPSM2, BDP1, EPS8, EPS8L2, and PCDH15)." (PMID 33809266, 2021). "Mutations in LOXHD1, OTOF, PCDH15, TBL1X, and TMC2 have been associated with hereditary disorders of balance, deafness or hearing loss in humans (NCBI gene db and GeneCards)." (PMID 32770228, 2020). "The Ames waltzer mouse carries mutations in Pcdh15, and exhibit similar symptoms to human USH1F patients, such as deafness, and show circling behaviors indicative of vestibular dysfunction." (PMID 33193648, 2020). "In the current study, we detected one reported and six novel mutations in 5 distinct deafness genes (TRIOBP, LHFPL5, CDH23, PCDH15, and MYO7A) in 5 recessive families." (PMID 29568747, 2018). "The most frequent causative gene revealed by this technology was CDH23 (n = 3), followed by MYO15A (n = 2), MYO7A (n = 2) and other four deafness genes (PCDH15 (n = 1), USH2A (n = 1), MYO3A (n = 1) and ACTG1 (n = 1))." (PMID 25373420, 2014). "The deafness of PCDH15-ΔCD2 mice has been attributed to defects in hair-bundle polarity, a phenotype consistent with Pcdh15-CD2 being an essential component of kinociliary links." (PMID 24940003, 2014).